F8 (coagulation factor VIII)
Diseases named in the same sentence as F8 in open-access papers (continued):
Sharing a sentence is not in itself a finding about the gene and the disease.
hemophilia A (continued). "An 8-year-old male with hemophilia A was diagnosed with HSP while receiving coagulation factor VIII replacement therapy in our hospital." (PMID 36859289, 2023). "Ultimately, the patient was diagnosed with haemophilia A. Hemorrhage controlled was obtained through coagulation factor VIII infusion." (PMID 37441981, 2023). "Haemophilia A is a rare, X chromosome-linked bleeding disorder caused by partial or total deficiency of coagulation factor VIII (FVIII)." (PMID 37537616, 2023). "The development of coagulation factor VIII (FVIII) inhibitory antibodies is a serious complication in hemophilia A (HA) patients after FVIII replacement therapy." (PMID 36569839, 2022). "The other SNP found only in Somalia is the hemophilia A variant rs137852380 (AAF 0.0105; 1%) in F8 gene (FVIII G89D)." (PMID 35337356, 2022). "Hemophilia is an X-linked recessive bleeding disorder caused by a deficiency of coagulation factor VIII (FVIII) or factor IX (FIX), which are named hemophilia A (OMIM#306700) and hemophilia B (OMIM#306900), respectively." (PMID 35269902, 2022). "We treated newborn (2-day old) hemophilia A (F8 knock out, KO) mice by i.v. administration of 2.5 × 1010 transducing units (TU)/kg of LV (n = 5–9 mice per LV) and measured FVIII blood concentration and activity overtime." (PMID 35508619, 2022). "There are two main types of hemophilia: hemophilia A, which is caused by a deficiency of coagulation factor VIII (FVIII) and accounts for 80–85% of the total hemophilia population, and hemophilia B, which is caused by a deficiency of coagulation factor IX." (PMID 35252176, 2022). "A major complication of hemophilia A therapy is the development of alloantibodies (inhibitors) that neutralize intravenously administered coagulation factor VIII (FVIII)." (PMID 36107620, 2022). "Hemophilia A is treated with human plasma coagulation factor VIII (FVIII) replacement therapy and Hemophilia B with coagulation factor IX, which is purified from prothrombin complex concentrate (PCC)." (PMID 36297304, 2022). "Hemophilia A is an X-linked, recessive disorder due to deficiency of factor VIII (encoded by the F8 gene), which is critical for blood clotting." (PMID 35897115, 2022). "Haemophilia A (HA) and haemophilia B (HB) are recessive, X-linked inherited blood disorders caused by a deficiency of coagulation factor VIII (FVIII) and factor IX (FIX) respectively." (PMID 33916890, 2021). "Acquired hemophilia A (AHA) is a different bleeding disorder to that of classic hemophilia A. It is an autoimmune-mediated bleeding disorder due to the presence of autoantibodies (inhibitors) directed against plasma coagulation factor VIII." (PMID 34659972, 2021). "However, there is a wide range of criteria that in addition to F8 gene mutations, different molecular mechanisms may be associated with hemophilia A. Various functions of FVIII could be related to the hypothetical small non-coding RNAs, located within the F8 gene sequence." (PMID 34316492, 2021). "Hemophilia A is a coagulation defect caused by F8 gene mutations and leads to the production of an abnormal coagulating Factor VIII (FVIII)." (PMID 34316492, 2021). "The downstream process of Adynovate® (a 20 kDa-di-PEGylated coagulation factor VIII for hemophilia A) consists of a single SEC step, in which Superose 6 is used as a stationary phase." (PMID 34490225, 2021). "People with hemophilia A (PwHA) have endogenous defective copies of the coagulation factor VIII gene, which in turn dramatically affects the blood coagulation cascade." (PMID 34035274, 2021). "Most commercial Fc-fusion proteins use protein A affinity chromatography as an initial capture step in their downstream processing, except for Nplate® and Eloctate® (a B domain-deleted coagulation factor VIII for hemophilia A)." (PMID 34490225, 2021).
hemophilia A (continued). "Severe haemophilia A (SHA) is a rare, X-linked genetic bleeding disorder, defined by a baseline coagulation factor VIII (FVIII) activity < 1%." (PMID 34155229, 2021). "One of the most immunogenic protein-based therapies is coagulation factor VIII (FVIII), which is missing or defective in the X-linked congenital bleeding disorder hemophilia A (HA)." (PMID 33651716, 2021). "The clot waveform analysis (CWA)-APTT method is capable of measuring very low coagulation factor VIII (FVIII) activities in hemophilia A and to detect early disseminated intravascular coagulation (DIC) using biphasic waveforms." (PMID 34945283, 2021). "Acquired hemophilia A is a rare autoimmune disease with clinically often significant bleeding diathesis resulting from circulating autoantibodies inhibiting coagulation factor VIII." (PMID 33121522, 2020). "Replacement therapy with coagulation factor VIII (FVIII) represents the current clinical treatment for patients affected by hemophilia A (HA)." (PMID 32265927, 2020). "Hemophilia, a hereditary monogenic x-linked inherited coagulation disorder, is defined by a loss in functional coagulation factor VIII (FVIII), hemophilia A, or factor IX (FIX), hemophilia B, proteins." (PMID 32670285, 2020). "Acquired hemophilia A (AHA) is an extremely rare and serious bleeding disorder caused by autoantibodies against coagulation factor VIII (FVIII)." (PMID 32953190, 2020). "Hemophilia A (HA) is associated with defects in the F8 gene, encoding coagulation factor VIII (FVIII)." (PMID 32781510, 2020). "Hemophilia A, an X-linked condition, is one of the most severe hereditary bleeding disorders caused by the deficiency of the coagulation factor VIII (FVIII)." (PMID 33552050, 2020). "We initially demonstrated that nanoparticles that co-encapsulated both rapamycin and antigen were effective at inducing durable antigen-specific immunological tolerance in vivo, including against coagulation factor VIII in a mouse model of hemophilia A." (PMID 32508839, 2020). "Coagulation factor VIII (FVIII) can be added to reduce the bleeding complications of patients with hemophilia A. However, FVIII has poor PK properties." (PMID 31816964, 2019). "Hemophilia A is caused by various mutations in the F8 gene, resulting in a deficiency of functional factor VIII protein (FVIII)." (PMID 31727959, 2019). "Coagulation Factor VIII (FVIII) replacement therapy in hemophilia A patients is complicated by the development of inhibitory antibodies, which often render the treatment ineffective." (PMID 30842776, 2019). "Hemophilia A is a genetic disorder characterized by deficiency in coagulation factor VIII (FVIII), and modern therapy revolves around prophylactic FVIII replacement." (PMID 30931491, 2019). "CAR-Tregs were also studied in Hemophilia A, where genetic mutations in F8 gene result in either reduced levels or altered functionality of the blood-clotting protein, Factor VIII (FVIII)." (PMID 31561568, 2019). "Hemophilia A and B are X-linked bleeding disorders resulting from deficiencies of coagulation factor VIII (FVIII) and factor IX (FIX), respectively." (PMID 31354709, 2019). "Severe hemophilia A Patients were regularly infused with coagulation factor VIII (30 IU/kg, 3–4 times a week) for secondary bleeding prevention." (PMID 31348267, 2019). "In the context of hemophilia A, liver-specific promoter and enhancer elements with a codon-optimized human coagulation factor VIII (hFVIII) gene have been engineered." (PMID 29883422, 2018). "Acquired hemophilia A (AHA) is a rare bleeding disorder due to acquired antibodies against coagulation factor VIII (FVIII)." (PMID 30473893, 2018). "In line with a previous report, describing the reduction of VWF plasma levels by FVIII infusion in haemophilia A patients, we repeatedly found a 2.5-fold increase in VWF plasma levels in F8-/y mice relative to F8+/y littermate controls." (PMID 28837614, 2017).
hemophilia A (continued). "Haemophilia A and B (HA and HB, respectively) are severe bleeding disorders caused by mutations in the genes encoding coagulation factor VIII (FVIII) or coagulation factor IX (FIX), respectively." (PMID 28384182, 2017). "Prevention and treatment of bleeding in patients suffering from hemophilia A are inconvenient due to repeated intravenous infusions owing to the short half-life of coagulation factor VIII (FVIII) in circulation." (PMID 28952523, 2017). "Our finding that F8 deficiency leads to increased plasmatic VWF levels in mice is in line with the published report that haemophilia A patients that were injected with FVIII concentrate showed reduced VWF plasma levels." (PMID 28837614, 2017). "Current treatment of hemophilia A (HemA) patients with repeated infusions of factor VIII (FVIII; abbreviated as F8 in constructs) is costly, inconvenient, and incompletely effective." (PMID 27766066, 2016). "Recombinant FVIIa is a hemostatic agent developed for the treatment of hemophilia A or B with inhibitors (antibodies) to coagulation factor VIII or IX." (PMID 29497641, 2015). "Hemophilia A (HA) is an X chromosome-linked bleeding disorder, caused by mutations in the F8 gene that results in a dysfunctional clotting Factor VIII (FVIII)." (PMID 26176629, 2015). "Hemophilia A (HA) is an X-linked recessive congenital coagulation disorder caused by a factor VIII (FVIII) deficiency, which results from mutations in the FVIII gene (F8)." (PMID 24317041, 2014). "The formation of inhibitory antibodies directed against coagulation factor VIII (FVIII) is a severe complication in the treatment of hemophilia A patients." (PMID 24244658, 2013). "Inhibitory antibodies directed against coagulation factor VIII (FVIII) can be found in patients with acquired and congenital hemophilia A. Such FVIII-inhibiting antibodies are routinely detected by the functional Bethesda Assay." (PMID 23626669, 2013). "Gene- or cell-based therapies aimed at creating delivery systems for coagulation factor VIII (FVIII) protein have emerged as promising options for hemophilia A treatment." (PMID 24358271, 2013). "The high-dose FVIII regimen was used in a 3-year-old Caucasian boy with severe congenital hemophilia A (endogenous FVIII level below 0.01IU/mL), the intron 22 inversion of the F8 gene and high-titer FVIII inhibitor." (PMID 23057781, 2012). "Development of inhibitory antibodies to coagulation factor VIII (fVIII) is the primary obstacle to the treatment of hemophilia A in the developed world." (PMID 23144741, 2012). "Similarly, the integration of coagulation factor VIII (FVIII) into the AAVS1 locus of hemophilia A (HA) patient-derived iPSCs supported stable FVIII expression in their endothelial derivatives." (PMID 41511364, 2026). "In individuals with severe haemophilia A (SHA), the risk for inhibitor development is increased by variants that are more likely to be null, such as inversions, complex structural variants, or nonsense (stop‐gain) variants of the F8 gene." (PMID 41071185, 2025). "The X-linked bleeding diseases hemophilia A and B are defined by a partial or total lack of coagulation factor VIII (FVIII) or IX (FIX)." (PMID 40649878, 2025). "Delivering functional F8 and F9 genes to hepatocytes via adeno-associated viral (AAV) vectors through a single intravenous infusion marks a significant advancement in the treatment of hemophilia A and B." (PMID 39895992, 2025). "The current standard of care for Hemophilia A (HA), a hereditary bleeding disorder caused by mutations in the Factor VIII (F8) gene, include FVIII replacement proteins, engineered clotting factors, and a broad array of new therapeutics including antibodies and gene therapy." (PMID 41573577, 2025). "Hemophilia A (HA) is an inherited bleeding disorder characterized by quantitative deficiency of coagulation factor VIII (FVIII) and caused by pathogenic variants in the factor 8 (F8) gene located on the X chromosome (Xq28)." (PMID 39202783, 2024).
hemophilia A (continued). "Hemophilia A related to coagulation factor VIII, primarily affects men in a hereditary manner." (PMID 38645492, 2024). "Coagulation factor VIII (FVIII), the gene mutated in hemophilia A, is naturally expressed by LSEC, thus we exploited GP64-LV to deliver a FVIII transgene under the control of the endogenous FVIII promoter and achieved therapeutic amounts of FVIII and correction of hemophilia A mice." (PMID 38684862, 2024). "Thus, this study demonstrated, for the first time, the feasibility and safety of lentiviral modification in ProliHHs to induce the expression of coagulation factor VIII in the treatment of haemophilia A." (PMID 37199059, 2023). "Hemophilia A (HEMA) is an X-linked bleeding disorder caused by reduced/absent coagulation factor VIII expression, as a result of pathogenic variants in the F8 gene." (PMID 37864173, 2023). "As the second predominant pathogenic mutation in hemophilia A severe patients, F8 Intron one inversion (Inv1) completely splits the F8 gene into two parts and disrupts the F8 transcription, resulting in no FVIII protein production." (PMID 36968612, 2023). "Valoctocogene roxaparvovec is an AAV5-mediated gene therapy undergoing clinical trials for the treatment of hemophilia A; it delivers a functional, codon-optimized, B-domain-deleted, human F8 gene under the control of a liver-specific promoter (AAV5-hFVIII-SQ)." (PMID 33910590, 2021). "Haemophilia A is a rare inherited disorder caused by diminished/absent coagulation factor VIII (FVIII) activity, which result in spontaneous haemorrhages." (PMID 34437573, 2021). "The newborn had a family history of hemophilia A, with an uncle diagnosed with hemophilia A. The neonate was diagnosed with congenital hemophilia A. After admission, he was treated with human coagulation factor VIII with standard dosage according to the guidelines for the management of hemophilia." (PMID 34635150, 2021). "Hemophilia-A is a common genetic abnormality resulted from decreased or lack of factor VIII (FVIII) pro-coagulantprotein function caused by mutations in the F8 gene." (PMID 34308578, 2021). "Another health problem, which could be treated with iPSC gene therapy is a debilitating disease, hemophilia A. It is a congenital bleeding disorder caused by dysfunction or, more often, quantitative deficiency of procoagulation factor VIII (FVIII)." (PMID 34067183, 2021). "The current standard of care in haemophilia A (HA) is treatment with exogenous coagulation factor VIII (FVIII) concentrates, which may be plasma-derived (pdFVIII) or produced using recombinant cell technology (rFVIII)." (PMID 34066835, 2021). "Human coagulation factor VIII (FVIII) is a key co-factor in the clotting cascade, the deficiency of which leads to Hemophilia A. Human plasma-derived (pdFVIII) and recombinant FVIII (rFVIII) had been used as effective products to prevent and treat bleeding episodes." (PMID 32442215, 2020). "Hemophilia A (HA) is an X-link recessive coagulation disorder caused by lack of coagulation factor VIII (FVIII) with an incidence of 1 in 5000 male births." (PMID 30670078, 2019). "Hemophilia A (MIM 306700) is a bleeding disorder caused by pathogenic variants in the F8 gene (Xq28) resulting in reduced coagulation factor (F)VIII levels, and a bleeding phenotype that is inversely proportionate to residual FVIII activity." (PMID 29490426, 2018). "Hemophilia, the most common and severe inherited bleeding disorders, is caused by a lack in the production of functional coagulation factor VIII (FVIII, hemophilia A) or IX (FIX, hemophilia B), resulting in recurrent and spontaneous bleeding in joints and muscles, and sometimes in vital organs." (PMID 28932649, 2017). "A previous study with coagulation factor VIII (FVIII) in hemophilia A mice have demonstrated that five co-injections of SVP-Rapa with FVIII provided better durability than three co-injections, with tolerance being maintained for at least five months after treatment." (PMID 28761815, 2017).
hemophilia A (continued). "Hemophilia A and B (OMIM #306700 and #306900), inherited as X-linked recessive traits, are the most common hereditary hemorrhagic disorders caused by a deficiency or dysfunction of blood coagulation factor VIII (FVIII) and factor IX (FIX)." (PMID 26258137, 2015). "Hemophilia A is a blood clotting disorder caused by a lack of functional blood coagulation factor VIII (fVIII), a protein cofactor essential to the intrinsic pathway of the blood clotting cascade." (PMID 26598467, 2015). "Hemophilia A is a hemorrhagic disease caused by insufficient levels or complete absence of functional coagulation factor VIII (FVIII) in the circulation." (PMID 25530931, 2013). "The quality of some of the human plasma derived drugs such as coagulation factor VIII and coagulation factor IX which can be used for the treatment of hemophilia A and B, depends on their activity which may be affected by filtration." (PMID 22615604, 2010). "Hemophilia A (OMIM: 306700), a rare X-linked recessive inherited hemorrhagic disorder with a prevalence rate of approximately 1 in 5,000 live male births, is characterized by the deficiency of the coagulation factor VIII (FVIII) due to a wide spectrum of pathogenic variants in the F8 gene." (PMID 41179498, 2025). "Acquired hemophilia A, a rare condition resulting in spontaneous bleeding without prior bleeding disorders, arises due to autoantibody-mediated inhibition of coagulation factor VIII and is typically associated with autoimmune, neoplastic, drug, or obstetric factors." (PMID 39220555, 2024). "In order to evaluate FVIII output and stability in adult mice, without confounding factors due to anti-FVIII immune responses, that are more likely to develop upon treatment at this age, we generated immune-deficient hemophilia A mice, by crossing F8 KO with Rag1 KO mice (RagHemoA)." (PMID 35508619, 2022). "Hemophilia A is an X-linked bleeding disease caused by reduced or absent activity of coagulation factor (F) VIII which is a consequence of mutations or deletions within the F8 gene." (PMID 32265927, 2020). "The lack of endogenous FVIII protein expression in severe hemophilia A patients with large mutations in the F8 gene results in ineffective FVIII Treg induction and Teff escape during thymic selection, reflected in the higher rate of inhibitor development for these patients." (PMID 30842776, 2019). "To systematically investigate the role of FVIII on VWF content in the liver endothelium, on VWF plasma levels, and VWF multimer size ex vivo, and to determine its implication in hepatic inflammation, we have used the F8-deficient haemophilia A mouse model on a pure C57BL/6J background." (PMID 28837614, 2017). "While null mutations in the F8 gene predispose severe hemophilia A patients to a 21-88% risk of antibody development, underlying risk diminishes to <10% in those with genotypes resulting in production of truncated nonfunctional FVIII." (PMID 23601343, 2013). "Haemophilia A and Haemophilia B are X-linked inherited bleeding disorder caused by a decreased activity or lack of coagulation factor VIII cofactor activity (haemophilia A) or coagulation factor IX enzyme activity (haemophilia B) due to heterogenous mutations in the F8 and F9 coding gene." (PMID 22423892, 2012). "Hemophilia A is an X-linked recessive disorder due to causal mutations in the F8 gene that lead to absent or decreased factor VIII (fVIII) activity and present phenotypically with abnormal bleeding, both trauma-induced and spontaneous that can be life-threatening." (PMID 23144741, 2012). "As the standard treatment for patients with hemophilia A, prophylaxis with coagulation factor VIII (FVIII) was proposed to maintain a steady trough FVIII level mainly to prevent spontaneous and breakthrough bleeds." (PMID 38478908, 2024).